CORO1C (coronin 1C)
Description:
Plays a role in directed cell migration by regulating the activation and subcellular location of RAC1. Increases the presence of activated RAC1 at the leading edge of migrating cells. Required for normal organization of the cytoskeleton, including the actin cytoskeleton, microtubules and the vimentin intermediate filaments (By similarity). Plays a role in endoplasmic reticulum-associated endosome fission: localizes to endosome membrane tubules and promotes recruitment of TMCC1, leading to recruitment of the endoplasmic reticulum to endosome tubules for fission. Endosome membrane fission of early and late endosomes is essential to separate regions destined for lysosomal degradation from carriers to be recycled to the plasma membrane. Required for normal cell proliferation, cell migration, and normal formation of lamellipodia (By similarity). Required for normal distribution of mitochondria within cells (By similarity). Interacts with GDP-bound RAB44 in bone marrow macrophages to promote osteoclastogenesis (By similarity). Involved in the migration and chemotaxis of macrophages (By similarity). [Isoform 3]: Involved in myogenic differentiation.
Synonyms: coronin-3; HCRNN4
Tractability: Antibody: UniProt places it where antibodies can reach, with high confidence; its Gene Ontology location is reachable by antibodies, with medium confidence. PROTAC: ubiquitination databases record sites on it; its protein half-life has been measured.
Gene: Protein-coding gene on chromosome 12 (108,645,109 to 108,732,563, reverse strand). Ensembl gene ENSG00000110880.
Subcellular location: Cell membrane; Cell projection, lamellipodium; Cell projection, ruffle membrane; Cytoplasm, cytoskeleton; Cytoplasm, cell cortex; Endosome membrane; Cell membrane, sarcolemma (Isoform 3); Cytoplasm, myofibril, sarcomere; Synapse
Gene Ontology:
Molecular function: actin filament binding; protein binding; small GTPase binding
Biological process: endosomal transport; endosome fission; endosome membrane tubulation; membrane fission; negative regulation of epithelial cell migration; negative regulation of focal adhesion assembly; negative regulation of protein kinase activity by regulation of protein phosphorylation; negative regulation of protein phosphorylation; negative regulation of substrate adhesion-dependent cell spreading; neural crest cell migration; positive regulation of lamellipodium morphogenesis; regulation of epithelial cell migration; regulation of focal adhesion assembly; regulation of protein phosphorylation; regulation of substrate adhesion-dependent cell spreading; actin filament organization; activation of GTPase activity; establishment of protein localization; macrophage chemotaxis; phagocytosis; positive regulation of osteoclast differentiation; regulation of fibroblast migration; signal transduction; negative regulation of cellular component organization; regulation of ruffle assembly
Cellular component: actin cytoskeleton; endosome membrane; focal adhesion; lamellipodium; lateral plasma membrane; plasma membrane; synapse; vesicle; actin filament; flotillin complex; cell cortex; cytoskeleton; ruffle membrane; sarcolemma; sarcomere
Genetic constraint (gnomAD): Loss-of-function variants: 10 observed, 44.66 expected, observed/expected ratio (o/e) 0.22, 90% interval 0.14 to 0.38. The upper end of that interval is the gene's LOEUF score, 0.38, which puts it in group 1 of 6, group 1 being the genes least tolerant of losing a copy. Missense variants: 371 observed, 561.89 expected, observed/expected ratio (o/e) 0.66, 90% interval 0.61 to 0.72. Synonymous variants: 167 observed, 197.11 expected, observed/expected ratio (o/e) 0.85, 90% interval 0.75 to 0.96.
Homologues: Orthologues: chimpanzee CORO1C (99% identical), macaque CORO1C (99% identical), dog CORO1C (99% identical), guinea pig CORO1C (99% identical), pig CORO1C (98% identical), rat Coro1c (98% identical), mouse Coro1c (97% identical), rabbit CORO1C (97% identical), tropical clawed frog coro1c (85% identical), zebrafish coro1cb (84% identical), zebrafish coro1ca (81% identical), Drosophila melanogaster coro (56% identical), and 1 more. Paralogues in human: CORO1B (73% identical), CORO6 (68% identical), CORO1A (63% identical), CORO2B (45% identical), CORO2A (44% identical), CORO7 (33% identical).
Diseases named in the same sentence as CORO1C in open-access papers:
CORO1C is named in the same sentence as 45 diseases in open-access papers, as found by Europe PMC text mining. Sharing a sentence is not in itself a finding about the gene and the disease. The quoted sentences say what the papers report.
gastric cancer (15 papers, 2012 to 2023). A primary or metastatic malignant neoplasm involving the stomach. "CORO1C, a member of coronin family, associates with poor survival rates in gastric cancer and promotes metastasis." (PMID 35593474, 2022). "RCC2, together with PAK4, were co-immunoprecipitated with CORO1C, whereas knockdown of PAK4 ceased the association of CORO1C with RCC2 in gastric cancer cells." (PMID 35593474, 2022). "Gastric cancer patients with positive CORO1C expression were associated with poor prognosis and lower survival rate." (PMID 30974047, 2019). "Gastric cancer patients with positive CORO1C expression exhibited a higher risk of lymph node metastasis (P = 0.005) and a worse clinical stage (P = 0.024) compared with patients with negative CORO1C expression." (PMID 30974047, 2019). "In addition, high expression of CORO1C is closely associated with a worse prognosis and aggressive pathological parameters in hepatocellular carcinoma, gastric cancer, and colorectal cancer." (PMID 37239355, 2023). "In gastric cancer, overexpressed CORO1C is associated with poor prognosis and could promote metastasis by regulating cyclin D1 and vimentin." (PMID 32695668, 2020). "Association of CORO1C expression with clinicopathological parameters from gastric cancer patients." (PMID 30974047, 2019). "Therefore the CORO1C–cyclin D1–vimentin pathway is in turn associated with the prognosis of gastric cancer patients." (PMID 30974047, 2019). "Coronin-1C was selected for further investigation as this protein has been associated with metastasis in a variety of cancers, including breast cancer and other malignancies such as lung, diffuse glioma, hepatocellular carcinoma and gastric cancer." (PMID 28302118, 2017). "Cyclin D1 and vimentin might mediate the oncogenicity in human gastric cancer caused by CORO1C." (PMID 30974047, 2019). "In gastric cancer cells, CORO1C expression facilitated cancer cell aggressiveness (e.g., cell viability, colony formation, and metastasis) by positively regulating cyclin D1 and vimentin expression." (PMID 37239355, 2023). "Aberrant expression of CORO1C has been reported in several types of human cancers, e.g., glioblastoma, hepatocellular cancer, breast cancer, non-small cell lung cancer, gastric cancer, and colorectal cancer." (PMID 37239355, 2023). "In this study, we explored the molecular mechanism by which Ser99-phosphorylated PAK4 is released from GEF-H1/Tctex-1 complex on microtubule and is recruited to the leading edge of the gastric cancer cell by binding to CE domain of CORO1C." (PMID 35593474, 2022). "In order to detect the effect of the interaction between PAK4 and CORO1C on the migration of gastric cancer cells, transwell assay was performed." (PMID 35593474, 2022). "It was also identified to be a necessary region both for the leaing edge localization of PAK4 and for PAK4/CORO1C-induced migration of gastric cancer cells." (PMID 35593474, 2022). "Our results confirmed that phosphorylation at serine 99 distributed PAK4 to the cell membrane, and interestingly, this phosphorylation is also required for CORO1C-promoted migration of gastric cancer cells." (PMID 35593474, 2022). "Here we discover that CORO1C, a member of coronin family that regulates microfilament and lamellipodia formation, recruits cytoplasmic PAK4 to the leading edge of gastric cancer cells by C-terminal extension (CE) domain of CORO1C (353–457 aa)." (PMID 35593474, 2022). "CORO1C has been confirmed to promote cellular proliferation and metastasis through regulating cyclin D1 and vimentin in gastric cancer, but little is known about the role of CORO1C in CRC." (PMID 34179087, 2021). "Reportedly, CORO1C overexpression is related to poor prognosis in hepatocellular carcinoma, primary effusion lymphoma, and gastric cancer." (PMID 34179087, 2021).
gastric cancer (continued). "It was demonstrated that knockdown of CORO1C dramatically suppressed cell viability, colony formation, mitosis, and metastasis and promotes apoptosis of gastric cancer cells." (PMID 34179087, 2021). "Knocking out CORO1C significantly reduced the total number of gastric cancer cells, inhibited cell viability, cell colony formation, mitosis, and metastasis, and promoted apoptosis." (PMID 34194957, 2021). "In gastric cancer, the knockdown of CORO1C markedly suppressed the malignant transformation of cancer cells." (PMID 34884487, 2021). "CORO1C is overexpressed in multiple types of clinically aggressive cancers, such as triple-negative breast cancer, gastric cancer and glioblastoma." (PMID 32206066, 2020). "In summary, we have demonstrated that CORO1C promoted both proliferation and metastasis, stimulated cellular mitosis and inhibited cell apoptosis in gastric cancer cells." (PMID 30974047, 2019). "Gastric cancer patients with positive expression of CORO1C showed both lower RFS rate and lower OS rate compared with patients with negative expression of CORO1C." (PMID 30974047, 2019). "Knocking down of CORO1C in gastric cancer cells notably promoted cellular apoptosis and inhibited the process of cell cycle." (PMID 30974047, 2019). "Both cellular migration and cellular invasion decreased notably after knocking down CORO1C by siCORO1C‐1 or siCORO1C‐2 compared with siNC in both gastric cancer cell lines BGC‐823 and AGS." (PMID 30974047, 2019). "As a result, CORO1C protein levels in gastric cancer tissues were higher compared with normal gastric tissues." (PMID 30974047, 2019). "Gastric cancer patients positive for CORO1C expression showed lower relapse‐free survival and overall survival rates." (PMID 30974047, 2019). "High expression levels of CORO1C were positively correlated with poor clinicopathological parameters in gastric cancer patients, including lymph node metastasis and clinical stage." (PMID 30974047, 2019). "As determined by immunohistochemistry, the protein levels of CORO1C were much higher in gastric cancer tissues than in normal gastric tissues." (PMID 30974047, 2019). "Knockdown of CORO1C dramatically suppressed total cell number, cell viability, cell colony formation, cell mitosis and cell metastasis, and promoted apoptosis of gastric cancer cells." (PMID 30974047, 2019). "As determined by cell functional assays, knocking down of CORO1C in gastric cancer cells significantly decreased cellular ability for growth and metastasis." (PMID 30974047, 2019). "For further study, cellular migration and invasion experiments were carried out to assess the functional role of CORO1C in cellular migration and invasion of gastric cancer cells." (PMID 30974047, 2019). "We analyzed the correlation between CORO1C expression and clinicopathological parameters in these 80 gastric cancer patients." (PMID 30974047, 2019). "Immunohistochemistry was performed to detect the protein levels of CORO1C in 80 human gastric cancer tissues and 80 normal gastric tissues." (PMID 30974047, 2019). "The expression levels of CORO1C were higher in stage III‐IV gastric cancer patients (80.8%) than in stage I‐II gastric cancer patients(57.1%)." (PMID 30974047, 2019). "Gastric cancer patients with positive CORO1C expression showed significantly lower RFS (P = 0.001) and OS (P = 0.003)." (PMID 30974047, 2019). "In this study, we systematically investigated the functional role of CORO1C in human gastric cancer." (PMID 30974047, 2019). "CORO1C is differentially expressed in various solid tumors, such as glioblastoma cancer, hepatocellular cancer, breast cancer, lung cancer, colorectal cancer and gastric cancer." (PMID 35593474, 2022). "Therefore, CORO1C also performed a promoting role in cellular metastasis of human gastric cancer cells." (PMID 30974047, 2019). "As cyclin D1 and vimentin play an oncogenic role in gastric cancer, CORO1C may exert its tumor‐promoting activity through these proteins." (PMID 30974047, 2019).
gastric cancer (continued). "Expression of CORO1C in gastric cancer and normal gastric tissues." (PMID 30974047, 2019). "Therefore, CORO1C inhibited cellular apoptosis and facilitated cell mitosis in gastric cancer cells." (PMID 30974047, 2019). "Therefore, the positive expression of CORO1C indicated poor prognosis in patients with gastric cancer." (PMID 30974047, 2019). "The positive expression of CORO1C also indicated poor prognosis in patients with gastric cancer." (PMID 30974047, 2019). "The CORO1C–Rac‐1–cyclin D1–vimentin pathway might also contribute to human gastric cancer and mediate the enhanced carcinogenicity of gastric cancer cells, which needs to be examined in future work." (PMID 30974047, 2019). "Compared with normal gastric tissues (40%), notably higher expression levels of CORO1C were detected in gastric cancer tissues (72.5%), suggesting that the occurrence of gastric cancer may be related to the high expression of CORO1C." (PMID 30974047, 2019). "Therefore, CORO1C was oncogenic in several kinds of human cancers, and here we have first proved the oncogenic role of CORO1C in human gastric cancer." (PMID 30974047, 2019). "The percentage of apoptosis increased, the proportion of cells in G1 phase increased and in S phase decreased significantly after depletion of CORO1C in gastric cancer cells, indicating that CORO1C depressed cell apoptosis and stimulated cellular mitosis in gastric cancer cells." (PMID 30974047, 2019). "Moreover, CORO1C expression levels in gastric cancer patients were negatively correlated with both overall survival (OS) rate and relapse‐free survival (RFS) rate." (PMID 30974047, 2019). "Moreover, overexpression of coronin-1C was found to correlate with lymph node spread and increased clinical stage in gastric carcinoma, possibly via the regulation of MMP-9 and cathepsin K." (PMID 28302118, 2017). "Therefore, CORO1C was a carcinogenic factor in gastric cancer, and it could serve as a potential target for gastric cancer diagnosis and therapy." (PMID 30974047, 2019). "Herein, we examined whether CORO1C was oncogenic for human gastric cancer." (PMID 30974047, 2019). "Therefore, the promoting role of CORO1C in both proliferation and metastasis of gastric cancer cells might be mediated by cyclin D1 and vimentin." (PMID 30974047, 2019). "Therefore, positive expression of CORO1C indicated poor prognosis in patients with gastric cancer." (PMID 30974047, 2019). "CORO1C could be used as a potential target for gastric cancer diagnosis and treatment." (PMID 30974047, 2019). "Therefore, cyclin D1 and vimentin might mediate the process of CORO1C increasing oncogenicity in human gastric cancer cells." (PMID 30974047, 2019). "Therefore, CORO1C possessed a tumor promoting role in human gastric cancer." (PMID 30974047, 2019). "Therefore, CORO1C played a promoting role in cellular proliferation of gastric cancer cells." (PMID 30974047, 2019). "We confirmed the interaction of CORO1C with PAK4 and found the colocalization of CORO1C with PAK4 on the membrane of gastric cancer cells." (PMID 35593474, 2022). "Once phosphorylated, PAK4 is released from microtubule, and then is recruited by CORO1C to the leading edge and regulates the CORO1C/RCC2 (regulator of chromosome condensation 2) complex, leading to the migration of gastric cancer cells." (PMID 35593474, 2022). "Once phosphorylated, PAK4 is released from microtubules, and then is recruited by CORO1C to the leading edge and regulates the CORO1C/RCC2 complex, leading to the migration of gastric cancer cells." (PMID 35593474, 2022). "In this context, the miR-1-mediated downregulation of the TMSB4X, CNN3, TWF1, CORO1C and WASF2 genes led to the inhibition of tumor cell metastasis of breast and gastric cancers." (PMID 28159933, 2017). "Most of the highest expressed circRNA genes in gastric cancer samples are also present in tumor-adjacent tissue (CFLAR, CORO1C, HIPK3, ASXL1 and SFMBT2)." (PMID 29109417, 2017).
gastric cancer (continued). "In the present investigation, miR-1 was shown to simultaneously inhibit tumor growth and metastasis of breast and gastric cancers by synchronously targeting CDK4 and TMSB4X, CNN3, TWF1, CORO1C and WASF2 genes." (PMID 28159933, 2017). "GST pull-down assay showed that though RCC2 interacted with CORO1C∆CE, the membrane co-localization of RCC2 with CORO1C∆CE disappeared, while further PAK4 knockdown also ceased both the interaction of RCC2 with CORO1C and the leading edge co-localization of RCC2 in gastric cancer cells." (PMID 35593474, 2022). "The result showed that overexpression of CORO1C promoted the migration of gastric cancer cells, but not CORO1CΔCE." (PMID 35593474, 2022). "Higher expression levels of CORO1C were detected in gastric cancer tissues as compared with normal gastric tissues." (PMID 30974047, 2019). "On the contrary, 58 out of 80 gastric cancer tissues showed positive expression of CORO1C (72.5%), and 22 out of 80 cases showed negative expression of CORO1C (27.5%) (P < 0.001)." (PMID 30974047, 2019). "In addition, CORO1C levels were found to be positively correlated with lymph node metastasis in gastric cancer patients." (PMID 30974047, 2019).